RNU6-1005P (RNA, U6 small nuclear 1005, pseudogene)
Gene: Small nuclear RNA gene on chromosome 16 (21,642,054 to 21,642,160, forward strand). Ensembl gene ENSG00000207248.
Homologues: Orthologues: chimpanzee U6 (100% identical), macaque U6 (97% identical), rabbit U6 (91% identical), mouse Gm25538 (88% identical), guinea pig U6 (83% identical). Paralogues in human: RNU6-16P (93% identical), RNU6-1 (92% identical), RNU6-12P (92% identical), RNU6-13P (92% identical), RNU6-17P (92% identical), RNU6-18P (92% identical), RNU6-2 (92% identical), RNU6-32P (92% identical), RNU6-39P (92% identical), RNU6-3P (92% identical), RNU6-4P (92% identical), RNU6-5P (92% identical), and 1286 more.